SPHK1 (sphingosine kinase 1)
Diseases named in the same sentence as SPHK1 in open-access papers (continued):
Sharing a sentence is not in itself a finding about the gene and the disease.
breast carcinoma (continued). "Previous studies suggested that the sphingosine kinase-1 (SPHK1) is a proposed regulator of breast cancer chemoresistance, and that cisplatin-resistant NSCLC cells overexpressed SphK162." (PMID 33753779, 2021). "Multiple clinical observations have subsequently reported the contribution of high SPHK1 expression to therapy resistance, disease recurrence and metastasis in breast cancer patients, all of which are similar to the clinical implications of breast CSCs." (PMID 34820423, 2021). "In this review, we first explore the key functions of sphingosine kinase 1 in human cancers, followed by a critical review of current findings on SPHK1 signaling, particularly in breast cancer." (PMID 34820423, 2021). "Previous immunohistochemical analysis of paraffin-embedded breast cancer tissues and cells indicated heterogeneous SphK1 and S1P3 nuclear localization." (PMID 33919234, 2021). "On the other hand, doxorubicin-resistant breast cancer cell lines showed a high expression of SPHK1 and its inhibition with fingolimod (immunosuppressive drug) caused a decrease in proliferation." (PMID 35004331, 2021). "Our demonstration that pro-proliferative signaling promotes SphK1 nuclear-localization in MCF-7 cells prompts further analysis of its cell-type-specific functions in breast cancer." (PMID 33919234, 2021). "We also discuss the therapeutic potentials and perspectives of targeting SPHK1 signaling in breast cancer and cancer stem cells." (PMID 34820423, 2021). "For instance, miR-515 is transcriptionally repressed by ERα and functions as a tumor suppressor in breast cancer cells by increasing the level of oncogenic sphingosine kinase 1 (SK1)." (PMID 33672261, 2021). "Nevertheless, it is anticipated that SPHK1 would act via different signalling pathways to regulate the survival of CSCs derived from different subtypes of breast cancer." (PMID 34820423, 2021). "Recently, it has been reported that SphK1 activation by estrogen receptor α36 contributes to tamoxifen resistance in breast cancer." (PMID 34948163, 2021). "The dependency of breast CSCs on SPHK1 underscores the great promise of targeting SPHK1 in the treatment of refractory breast cancer." (PMID 34820423, 2021). "We also discuss current therapeutics and perspectives of targeting SPHK1 signaling in breast cancer and cancer stem cells." (PMID 34820423, 2021). "Nevertheless, evidence to date has uniformly supported a rationale of targeting SPHK1/S1P axis in breast cancer which warrants further therapeutic development." (PMID 34820423, 2021). "They reported that miR-515-5p downregulation increases the proliferation of breast cancer cells and estrogen-dependent SphK1 activity." (PMID 35201458, 2021). "Immunohistochemical analysis of mammary tumors indicated that nuclear SphK1 can co-localize with Erk1/2, Lck/Yes novel tyrosine kinase (LYN), V-akt murine thymoma viral oncogene homolog (AKT), or Nuclear Factor κB (NF-κB)." (PMID 33919234, 2021). "Using a kinome-wide shRNA library screen, we previously identified that SPHK1 is required for breast cancer cell survival." (PMID 32260399, 2020). "In those reports, miR-124 targeted SphK1 and Cdk4 in squamous carcinoma and breast cancer cells, respectively." (PMID 32963317, 2020). "In the present study, we also analyzed the expression of SPHK1 in breast cancer in local and TCGA cohort." (PMID 32170160, 2020). "In our previous studies, we confirmed that increased phospho-Sphk1 or phospho-SphK2 was correlated with the increased S1P in breast cancer cells." (PMID 32796926, 2020). "We have previously reported that SphK1-generated S1P links chronic inflammation and metastasis, and shortens the survival of mice and patients with breast cancer." (PMID 32933189, 2020). "Targeting SphK1 in triple-negative MDA-MB-231 breast cancer cells decreased proliferation and survival by compromising protein kinase C activity and cytokinesis." (PMID 31752564, 2020).
breast carcinoma (continued). "This is consistent with our previous report showing that both SphK1 and SphK2 are important for insulin-induced growth in breast cancer cells." (PMID 32796926, 2020). "This study provides a significant understanding of SphK1 inhibitors that can be used in the development of potential therapeutics against breast cancer." (PMID 31752564, 2020). "Our group was the first to demonstrate the mechanism of how S1P is generated inside a breast cancer cell by SphK1, where SphK2 is often suppressed in a compensatory manner, and is then exported out of breast cancer cells by transporters including SPNS2." (PMID 32933189, 2020). "Several preclinical studies have used mouse breast cancer models to investigate the effects of SphK1 inhibitors on tumour growth." (PMID 31752564, 2020). "Until now, only few inhibitors are known to be effective in inhibition of SphK1 in breast carcinoma but were found to have poor pharmacokinetics profile, cytotoxic at micro molar concentration and ineffective for persistent survival rate in human trials." (PMID 31752564, 2020). "It is now well-established that sphingosine kinase 1 (SK1) plays a significant role in breast cancer development, progression, and spread, whereas SK1 knockdown can reverse these processes." (PMID 32266132, 2020). "It has been observed that SphK1, a kinase that generates S1P, is highly elevated in multiple carcinomas including breast carcinoma." (PMID 31752564, 2020). "Sphingosine kinase 1 (SphK1) is a promising therapeutic target against several diseases including mammary cancer." (PMID 31752564, 2020). "Current studies in solid tumors found several molecules with relatively more direct interaction to icaritin above the common signal pathways, such as estrogen receptor in breast cancer cells and sphingosine kinase 1 in hepatocellular carcinoma cells." (PMID 31032347, 2019). "Activation of SPHK1 encourages tumor progression by promoting angiogenesis and lymphangiogenesis in human breast cancer cells." (PMID 31101115, 2019). "Consistent with previous human breast cancer reports, our current study showed that levels of SPHK1 were higher in FMTs compared with normal tissue from the same patient." (PMID 31101115, 2019). "The first, SKI-I, is a slightly stronger inhibitor of SPHK1 versus SPHK2 and blocks SPHK1 activity in vitro to decrease JC mammary tumor growth." (PMID 31807117, 2019). "In the present study, the expression level of SPHK1 was examined in feline mammary tumor (FMT) specimens, and the IHC expression level of SPHK1 was associated with the histological grade of FMTs." (PMID 31101115, 2019). "In breast cancer, the SphK1/S1P/S1PR1 axis is critically involved in regulating numerous cellular processes, including cell growth, survival, invasion, vascular integrity, immune cell trafficking, angiogenesis, and cytokine and chemokine production." (PMID 31807117, 2019). "In Nagahashi et al49 recent study, they used FTY720 to target SPHK1/S1P/S1PR1 axis and suggested that this pathway is associated with obesity‐related inflammation and breast cancer metastasis." (PMID 29923327, 2018). "Epidermal growth factor receptors (EGFR) not only influence the estrogen pathway and regulate breast cancer cell survival and spreading, but also influence the SphK1 network." (PMID 29385066, 2018). "SphK1 product S1P can initiate tyrosine phosphorylation of EGFR in breast cancer cells, which was consistent with the observations previously reported in vascular smooth muscle cells and fibroblasts." (PMID 29385066, 2018). "SphK1 was also shown to stimulate HER2-positive breast cancer development through increased claudin-2 expression." (PMID 29385066, 2018). "An increased pathological complete response rate was also observed in tumors with high SphK1 expression within the luminal mammary cancer subtype group." (PMID 29385066, 2018).
breast carcinoma (continued). "Immunohistochemistry (IHC) analysis of ER-positive mammary tumors indicated that nuclear SphK1 can co-localize with ERK-1/2, LYN, AKT, or NF-κB within the space of the nuclear envelope." (PMID 29385066, 2018). "It has also been shown that SphK1 expression correlates with poor prognosis of breast cancer patients." (PMID 28912626, 2017). "IHC assay of breast cancer showed that the major source of SPHK1 expression is carcinoma cells that finally lead to produce S1P, which is the cause of angiogenesis, lymphangiogenesis, cell survival, and migration." (PMID 29531546, 2017). "Overexpression of SphK1 and differential S1PRs distribution are associated with poor prognosis and disease stage in breast cancer and may prove to be strong candidates as diagnostic and prognositic markers for ER+ and ER- breast cancers, endocrine resistance, and metastasis." (PMID 28415564, 2017). "Knockdown of SphK1 using siRNA in glioma and breast cancer cell models decreases S1P levels with an accompanying accumulation of ceramide resulting in increased apoptosis." (PMID 28415564, 2017). "An enhanced proliferation and decreased apoptosis correlated with high SphK1 expression in mouse breast cancer cells." (PMID 29149079, 2017). "In order to further understand the prognostic and therapeutic implications of IGF1R and SphK1 co-expression in breast cancer we have analyzed their distribution in human breast cancer formalin-fixed paraffin embedded (FFPE) tissue samples." (PMID 29207959, 2017). "A total of 120 human breast cancer tissue specimens were analyzed for SPHK1 expression using Quantitative Real–Time Polymerase Chain Reaction (q RT-PCR) assay." (PMID 29531546, 2017). "High expressions of S1PR1, S1PR3, and the S1P generating enzyme SphK1 have been reported in breast cancer patients." (PMID 29149079, 2017). "In estrogen receptor (ER) positive breast cancer cells overexpression of SphK1 increases tamoxifen resistance and ablation of SphK1 restores tamoxifen sensitivity." (PMID 28415564, 2017). "The observation that high IGF1R and SphK1 expression are prognostic for improved overall survival is paradoxical, given that the literature suggests IGF1R and SphK1 are oncogenic mediators in breast cancer." (PMID 29207959, 2017). "SPHK1 and S1PR3 expression in human breast cancer tissue is associated with reduced time to recurrence and cumulative disease-specific survival." (PMID 27129165, 2016). "SPHK1 or S1PR3 knockdown in breast cancer cells effectively reduced tumor growth and lung metastasis in vivo." (PMID 27129165, 2016). "Coexpression of Sphk1 and cyclinD1 has been detected in breast tissue, in abnormally growing cells and in breast cancer cells." (PMID 27811358, 2016). "Sphingosine kinase 1 (Sphk1), a key enzyme involved in membrane lipid metabolism, is highly expressed in breast cancer." (PMID 27811358, 2016). "Sukocheva and coworkers showed in MCF-7 breast cancer cells that estradiol increased SphK1 activity and the formation of S1P, with subsequent binding of S1P to one of its receptors, S1P3, which in turn transactivated EGFR." (PMID 26221601, 2015). "For example, silencing the expression of SPHK1 in glioblastoma cells and breast cancer cells induced cell cycle arrest, and inhibition of SPHK1 dramatically decreased breast cancer formation." (PMID 26311741, 2015). "Recently, SPHK1 was shown to increase S1P export from ER-positive breast cancer cells in response to estrogen." (PMID 25153718, 2014). "10% FBS was used to stimulate SPHK1 activity and examine the SPHK1-dependent mechanisms induced by serum for breast cancer cell survival." (PMID 25153718, 2014). "Both SPHK1 protein expression and SPHK1 activity were also higher in breast cancer cell lines compared to MCF-10A." (PMID 25153718, 2014). "Previous work in breast cancer has shown that SPHK1 is activated by estrogen signaling and promotes estrogen-dependent oncogenesis." (PMID 25153718, 2014).
breast carcinoma (continued). "Real-time PCR showed that SPHK1 mRNA expression was higher in breast cancer cell lines compared to MCF-10A." (PMID 25153718, 2014). "Using human breast cancer microarray data from Affymetrix U133A and U133Plus2 platforms, we found that basal-like subtype exhibits the highest SPHK1 gene expression among the various molecular subtypes." (PMID 25153718, 2014). "We next determined the effects of the SPHK1 pharmacological inhibitor SKI-5C on the colony formation ability of breast cancer cells." (PMID 25153718, 2014). "Numerous studies have shown that SPHK1 is critical for growth, metastasis and chemo-resistance of human breast cancers." (PMID 25153718, 2014). "Among the various molecular subtypes of breast cancer, it was observed that TNBCs express elevated levels of sphingosine kinase 1 (SPHK1) compared to other breast tumor subtypes." (PMID 25153718, 2014). "We will also show that SphK-1 is present in a catalitycally active form in vesicles shed by SK-Hep1 and human breast carcinoma 8701-BC cells." (PMID 20508814, 2010). "Furthermore, their pronounced ability to significantly reduce Sphk1 expression in MCF-7 cells highlights the potential of Sphk1 as a therapeutic target for breast cancer." (PMID 40358625, 2025). "SPHK1 promotes chemotherapy resistance in leukaemia, prostate and breast cancer." (PMID 40356021, 2025). "Moreover, a study in breast cancer cells has shown that insulin can also mediate mitogenic effects via both SPHK1 and SPHK2." (PMID 36979912, 2023). "In breast cancer, a high-fat diet and obesity upregulate SPHK1 expression leading to increased S1P." (PMID 36823149, 2023). "Another study showed that, in breast cancer, SPHK1 and ceramide galactosyltransferase (UGT8) are highly expressed in ER-negative tumors, and dihydroceramide synthases (LASS4 and LASS 6), acid ceramidase (ACDase), and glucosylceramide synthase (GCS) are highly expressed in ER-positive samples." (PMID 35965565, 2022). "When SphK1 isoform expression status was considered by breast cancer grade and by hormonal status (ER+ or ER−), we found that most of Grade 1, 2, IDC, and ILC tissue resections had undetectable levels of SphK1b isoform, whereas all Grade 3 breast tissues proved positive for SphK1b expression." (PMID 36532885, 2022). "As mentioned, the localization of SphK1 has been identified as a marker of breast cancer prognosis." (PMID 36532885, 2022). "Moreover, it has been reported that S1P generated from SphK1 accelerates breast cancer cell migration." (PMID 33968977, 2021). "The signaling role of SphK1 is different and considered pro-oncogenic in breast cancers." (PMID 33919234, 2021). "Similarly, epidermal growth factor activation of SphK1 is significant for the migration of breast cancer cells." (PMID 33920887, 2021). "Therefore, this study investigated growth- or apoptosis-triggered SphK1 trafficking in breast cancer cells." (PMID 33919234, 2021). "S1P, S1PRs, and SPHK1 expression are related to metastatic progression in breast cancers in vivo." (PMID 34283088, 2021). "Interestingly, SphK1 and SphK2 appear to have opposite effects in cancer: SphK1 is considered pro-oncogenic in breast cancers, while SphK2 was shown to facilitate antiproliferative signaling." (PMID 33919234, 2021). "Furthermore, recent studies have identified a role of SPHK1 in mediating survival of breast cancer stem cells (CSCs)." (PMID 34820423, 2021). "Given the synergistic effects of PF543 and doxorubicin on breast CSCs and non-CSCs in our study, it was proposed that neoadjuvant treatment with SPHK1 inhibitors with doxorubicin would reduce both CSCs and non-CSCs and thereby potentially improve therapeutic response in breast cancer patients." (PMID 32260399, 2020). "S1P is produced by SphK1 and interacts with components in the tumor microenvironment, which may regulate breast cancer metastasis." (PMID 31935914, 2020).
breast carcinoma (continued). "The recent computational approaches were employed to study and discover new SphK1 inhibitors that could be a starting point for a promising drug candidate in the treatment of breast cancer." (PMID 31752564, 2020). "Recent studies also indicated that SPHK1-S1P may play a role in regulating CSCs populations in breast cancer models." (PMID 32260399, 2020). "In addition, overexpression of SPHK1 in breast cancer cells was reported to increase breast CSCs and the tumorigenicity of tumors in nude mice via S1P binding to S1P3 and down-stream stimulation of Notch and p38 MAPK signaling." (PMID 32260399, 2020). "High levels of SPHK1 were shown to enhance tumor formation in breast cancer MCF-7 cells." (PMID 32170160, 2020). "The expression level of SphK1 was examined in feline mammary tumour specimens and found that SphK1 plays an important role in feline mammary tumours and may be used as therapeutic target." (PMID 31752564, 2020). "Upregulation of SPHK1 has been reported to have the potential to act as a prognostic biomarker in many human cancers, including oral squamous cell carcinoma, prostate cancer, gastric cancer, astrocytoma, and breast cancer." (PMID 31101115, 2019). "We were interested in determining whether SPHK1 is dysregulated in FMTs, which are similar to human breast cancers." (PMID 31101115, 2019). "Indeed, high expression of SphK1 induces a desensitization/tolerance to HER2-mediated signaling in ER+/HER2+ breast cancer cells." (PMID 30319979, 2018). "Similarly, the estrogen receptor modulator tamoxifen stimulated expression of SphK1 in antiestrogen resistant breast cancer cells in vitro." (PMID 29385066, 2018). "FTY720 has been demonstrated as a competitive inhibitor (with sphingosine) of SPHK1 with a Kic of 2 μmol/L and destabilizes SPHK1 by facilitating SPHK1 degradation via ubiquitination in human pulmonary artery smooth muscle, breast cancer, and androgen-independent prostate cancer cells." (PMID 31891125, 2018). "In estrogen receptor positive (ER+) tumors high S1PR1 and S1PR3 were reported to be causally associated with tamoxifen resistance and poor prognosis, and in vitro, in ER+ MCF-7 breast cancer cells, the SphK1/S1PR3 loop promoted breast cancer progression and migration." (PMID 28415564, 2017). "It is well accepted that IGF1R can regulate ER, and SphK1 is regulated by estrogen, in breast cancer, hence the therapeutic implication that co-targeting them may be clinically effective in ER-positive breast cancer." (PMID 29207959, 2017). "In addition, enforced overexpression of Sphk1 in human breast cancer cell line MCF-7 cells enhanced cell proliferation and resistance to tamoxifen-induced cell growth arrest and apoptosis." (PMID 28991193, 2017). "Knockdown of SPHK1 or S1PR3 reduced breast cancer cell tumorigenicity." (PMID 27129165, 2016). "Although the transcription factor via which Sphk1 signaling increases cyclinD1 expression has not yet been identified, that levels of the p65 subunit of NF-κB are increased in breast cancer specimens, and its expression is associated with cell progression." (PMID 27811358, 2016). "The regulation of both ERK1/2 and AKT activation in response to serum stimulation could represent potential mechanisms by which SPHK1 promotes survival in breast cancer cells." (PMID 25153718, 2014). "Even though ASAH1 and SPHK1 are sequential enzymes of the same pathway and have been functionally linked high ASAH1 expression has been associated with a positive outcome in epithelial ovarian and estrogen receptor positive breast cancers." (PMID 24970218, 2014). "However, the basal molecular subtype of breast cancers, which often lack the ER receptor and are thus unresponsive to anti-estrogens, have been found to express high baseline expression levels of SPHK1." (PMID 25153718, 2014).